EGR1 (early growth response 1)
Diseases named in the same sentence as EGR1 in open-access papers (continued):
Sharing a sentence is not in itself a finding about the gene and the disease.
osteosarcoma (continued). "To examine the function of EGR1 in osteosarcoma, we assessed the tumour growth and invasion in vitro and in vivo." (PMID 21283769, 2011). "Real-time PCR revealed that the 5 of 5 osteosarcoma cell lines exhibited 0.002- to 0.369-fold decreased in expression of EGR1." (PMID 21283769, 2011). "We showed that low-dose anti-tumor agent treatment up-regulated EGR1 expression and that EGR1 prevented osteosarcoma invasion via uPA/uPAR down-regulation." (PMID 21283769, 2011). "To investigate the effects of EGR1 on osteosarcoma tumor migration and invasion in vivo, we used a novel osteosarcoma murine xenograft model with 143B cells." (PMID 21283769, 2011). "Real-time PCR revealed that EGR1 was down-regulated both in osteosarcoma cell lines and osteosarcoma patients' biopsy specimens." (PMID 21283769, 2011). "Xenograft mice models showed that forced expression of EGR1 prevents osteosarcoma cell migration into blood vessels." (PMID 21283769, 2011). "We attempt to clarify the changes in EGR1 expression following low-dose anti-tumor agent treatment, and determined anti-tumor drug concentrations required to prevent osteosarcoma cell proliferation." (PMID 21283769, 2011). "We then examined the cellular mechanisms by which EGR1 exerts its effects on osteosarcoma cell invasion." (PMID 21283769, 2011). "In summary, anti-tumor agents increased the expression of EGR1, and EGR1 decreased osteosarcoma invasion." (PMID 21283769, 2011). "Thus, our data suggest that EGR1/LINC00857/miR‐105‐5p/c‐Myc axis plays an important role in Scutellarin‐inhibited osteosarcoma cell growth." (PMID 34346162, 2021). "On the other hand, both NFKB1 and EGR1 have been found to regulate the two dysfunction modules, which may also be key regulators involved in the pathogenesis of osteosarcoma." (PMID 30936265, 2019). "In addition, EGR1 was up-regulated both in osteosarcoma patient' specimens and osteosarcoma cell lines following anti-tumour agent treatment." (PMID 21283769, 2011). "We therefore, transfected the EGR1 expression vector and examined osteosarcoma cell growth." (PMID 21283769, 2011). "We investigated the expression of EGR1 in human osteosarcoma cell lines and biopsy specimens." (PMID 21283769, 2011). "We therefore examined the expression and function of EGR1 in osteosarcoma." (PMID 21283769, 2011). "We next examined the effects of EGR1 on anchorage-independent osteosarcoma growth." (PMID 21283769, 2011). "Our findings suggest that even though chemotherapy could not prevent osteosarcoma growth in chemotherapy poor responders, chemotherapy prevents osteosarcoma cell migration into blood vessel by down-regulation of urokinase plasminogen activation via up-regulation of EGR1 during chemotherapy periods." (PMID 21283769, 2011). "However, the role of EGR1 in the treatment of osteosarcoma by Scutellarin is still unknown." (PMID 34346162, 2021). "Real-time PCR revealed that forced expression of EGR1 in 143B, Saos-2, and HOS osteosarcoma cell lines decreased the expression of uPA and uPAR." (PMID 21283769, 2011). "In rat osteosarcoma cells, EGF induces the expression of Egr-1 mRNA, thus increasing mitogenesis." (PMID 34955078, 2022). "And there were 38 endogenous genes (including ARF1, HSP90AB1, and TUBA1B), 53 TFs (including E2F1, NFKB1, and EGR1), and 858 ncRNAs (including MALAT1, miR-590-3p, and TUG1) were considered as key regulators of osteosarcoma through a series of function enrichment analysis and network analysis." (PMID 30936265, 2019). "Although forced expression of EGR1 did not prevent osteosarcoma growth, forced expression of EGR1 prevented osteosarcoma cell invasion in vitro." (PMID 21283769, 2011). "We treated osteosarcoma cell lines with anti-tumor agent and some specific inhibitors including ERK inhibitor, HIF1-α inhibitor, JAK2 inhibitor, LY294002, and others but we were unable to inhibit EGR1 expression effectively." (PMID 21283769, 2011).
osteosarcoma (continued). "EGR1 was up-regulated by γ-secretase inhibitor in human osteosarcoma cell lines (data not shown)." (PMID 21283769, 2011). "MTT assay revealed that forced expression of EGR1 did not prevent osteosarcoma growth in vitro." (PMID 21283769, 2011).
Hypertension (11 papers, 2014 to 2025). The presence of chronic increased pressure in the systemic arterial system. "In the Rat Genome Database, Egr1 is on the list of genes associated with hypertension." (PMID 40806189, 2025). "In addition, ROS was associated with the up-regulation and activation of Egr-1 in hypoxia induced pulmonary fibrosis, hypertension, apoptosis and atherosclerosis." (PMID 27173006, 2016). "There were several genes affected by high-intensity interval training during HFD hypertension, which were Trim39, Nr4a1, Plekhf1, Tgm2, Lgals1, Egr1, and Atf3." (PMID 41516177, 2025). "In a previous experiment involving an animal model of hypertension, EGR1 was found to be the target gene of hsa-mir-124-3p." (PMID 38368317, 2024). "EGR1 is crucial for intimal hyperplasia and vascular remodeling after vascular injury, balloon injury, arterial hypertension, and chemical damage." (PMID 34421628, 2021). "Thus it is likely that Egr1 is related to oxidative stress-induced programmed hypertension." (PMID 25517031, 2014).
pulmonary fibrosis (11 papers, 2011 to 2025). Chronic progressive interstitial lung disorder characterized by the replacement of the lung tissue by connective tissue, leading to progressive dyspnea, respiratory failure, or right heart failure. "EGR1 is a candidate transcription factor in this pathway because it has been reported downstream of TGFβ1 signaling in human dermal fibroblasts, and the EGR1-TGFβ1 relationship is important in a murine model of pulmonary fibrosis." (PMID 33640015, 2021). "Previous studies demonstrated Egr-1 exhibiting potent stimulatory action on fibrotic gene expression and correlating with human fibrotic disorders like emphysema, pulmonary fibrosis and systemic sclerosis." (PMID 27173006, 2016). "In addition to Egr1, ICOS has been reported that it isto be positively associated with the amount of ILC2s in the blood of patients with idiopathic pulmonary fibrosis." (PMID 36776864, 2023). "But how Egr-1 affects the process of pulmonary fibrosis especially silicosis was seldom reported." (PMID 23874821, 2013). "In addition, Egr-1 levels were increased in vivo in lung tissues of patients with idiopathic pulmonary fibrosis and in lesional skin and lung from patients with scleroderma." (PMID 21365018, 2011). "Therefore, Egr-1 plays a critical mediator in SARS-CoV PLpro induced pathogenesis, as a potential therapeutic target to prevent the pulmonary fibrosis induced by SARS-CoV." (PMID 27173006, 2016). "Therefore, regnase-1 is regarded as a crucial posttranscriptional regulator for the pro-fibrotic function of ILC2s in mice and humans, and its regulatory mechanism for Egr1 and ICOS may provide novel therapeutic strategies for idiopathic pulmonary fibrosis." (PMID 36776864, 2023).
pulmonary hypertension (11 papers, 2011 to 2025). Increased pressure within the pulmonary circulation due to lung or heart disorder. "Pulmonary hypertension has been linked to reduced XO activity through the early growth response-1 (Egr-1) signaling pathway." (PMID 35783193, 2022). "Additionally, the EGR1-related pathway in endothelial cells derived from pluripotent stem cells contributes to the development of pulmonary hypertension associated with Down syndrome." (PMID 40811488, 2025). "However, one report suggests that Egr1 is significantly associated with right ventricular hypertrophy due to pulmonary hypertension." (PMID 38402404, 2024). "The neonatal calf is particularly susceptible to hypoxia-induced pulmonary hypertension, with severe inflammation, pulmonary vascular remodeling and pulmonary hypertension, and Egr-1 is increased in the pulmonary artery in the chronically hypoxic neonatal calf." (PMID 22140445, 2011). "Therefore, Egr-1 can play a critical role in pulmonary vascular remodeling though its regulation in pulmonary hypertension by ROS is not clearly understood." (PMID 22140445, 2011). "Thus, Egr-1-targeting DNAzymes are involved in the initiation and progression of pulmonary vascular remodeling in flow-related pulmonary hypertension and could serve as a potential target for PAH therapy in the future." (PMID 37057102, 2023). "Therefore, it can be inferred that EGR1 may play a significant role in contributing to lung injury following DHCA, primarily by promoting pulmonary inflammatory responses, facilitating cell apoptosis, and exacerbating pulmonary hypertension." (PMID 40811488, 2025).
B cell lymphoma (10 papers, 2013 to 2025). "EGR1 induces survival and a proliferative response in quiescent cells and is a major driver of mature B-cell lymphomas." (PMID 33833385, 2021). "EGR1 or early growth response 1 is a master regulator of hematopoietic differentiation, and studies demonstrated that the dysregulation of EGR1 is involved in hematologic malignancies such as chronic lymphocytic leukemia and B cell lymphoma." (PMID 31139332, 2019). "Moreover, Epstein-Barr virus (EBV) latent membrane protein-1 (LMP-1) increases genomic instability through early growth transcription response-1 (Egr-1) mediated upregulation of AID in B-cell lymphoma." (PMID 25834572, 2015). "Curcumin also repressed the growth of B lymphoma cells through suppression of the egr-1 gene (known as nerve growth factor-induced protein A) expression, which affected the suppression of the c-myc gene and the anti-apoptotic protein bcl-XL in BKS-2 cells (immature B cell lymphoma)." (PMID 31590362, 2019).
emphysema (10 papers, 2008 to 2023). "Egr-1 induction by cigarette smoke varies by strain, with marked increase in the emphysema-susceptible AKR/J mice as compared to the relatively resistant NZWLac/J strain." (PMID 23450717, 2013). "In Egr-1 (whose expression changes significantly in COPD)–deficient mice, resist cigarette smoke induced autophagy, apoptosis and emphysema, suggesting that autophagy provides a protective effect in CSE-induced COPD." (PMID 24447518, 2014). "Elevated egr-1 mRNA or protein has been widely detected in fibrotic tissues, including fibrotic kidneys, lung tissues from patients with emphysema." (PMID 23874821, 2013). "Egr-1−/− mice, which displayed basal airspace enlargement, resisted cigarette-smoke induced autophagy, apoptosis, and emphysema." (PMID 18830406, 2008). "Furthermore, the genetic depletion of LC3-II or Egr-1 (early growth response-1), a molecule involved in LC3B transcription, was associated with a resistance to emphysema in mice after exposure to cigarette smoke." (PMID 28344236, 2014). "Other implicated pathways in smoke related emphysema include the TGF-β signaling pathway via SMAD-3, cytokine IL-6, VEGF, and autophagy via early growth response-1 (Egr-1) and the protein microtubule-associated protein 1 light chain-3B (LC3B)." (PMID 23450717, 2013). "Expression of the transcription factor EGR1 is rapid and of short duration after acute tissue injury, hypoxia and pneumonectomy, although a prolonged expression has been found in lung tissue from patients suffering from advanced stage emphysema." (PMID 23056572, 2012). "Recent studies from this laboratory have revealed that Egr-1 may play a role in cigarette smoke induced lung pathophysiology by regulating the expression of matrix metalloproteinase-2, a candidate molecule in emphysema development." (PMID 18830406, 2008). "Furthermore, E2F4 has been found to form a complex with EGR-1 (a highly significant transcription factor in ECLIPSE and LT-CDNM) in response smoke exposure, which may lead to autophagy, apoptosis and subsequently to development of emphysema." (PMID 29237467, 2017).
epilepsy (10 papers, 2013 to 2023). A brain disorder characterized by episodes of abnormally increased neuronal discharge resulting in transient episodes of sensory or motor neurological dysfunction, or psychic dysfunction. "A strong enrichment was also observed for the proto-oncogenes FBJ osteosarcoma oncogene (Fos) and Jun (Jun), two TFs known as immediate early genes (IEGs), a group of TFs that also includes the previously identified epilepsy-associated TF Egr1 7,8." (PMID 38092829, 2023). "Activation of early growth response 1 (EGR1) causes a decrease in VIM expression, which also contributes to a reduction in neuronal damage and prevents the progression of epilepsy." (PMID 38067243, 2023). "It was previously shown that multiple IEGs, including Egr1, Egr4, c-Fos, c-Jun, Naps4, Nur77, and Arc were upregulated in in vivo animal (from rodents to primates) and in in vitro models of epilepsy, as was confirmed in our study." (PMID 37234916, 2023). "Thus, suppression of Fos and Egr1 mRNA expression are consistent with ameliorative drug effects on seizures, epileptogenesis and/or epilepsy." (PMID 24282673, 2013). "Notably, upregulation of NOVA1, neuroLSD1, and of the IEG proteins NR4A1, EGR1, and NPAS4 has been observed in patients with epilepsy and/or in epileptic mouse models, and their deregulation might contribute to DEE9 epileptic phenotype." (PMID 35613587, 2022).
fibrosis (10 papers, 2011 to 2025). the formation of excess fibrous connective tissue in an organ or tissue in a reparative or reactive process. "To elucidate Egr-1 function in SSc-associated fibrosis, we examined change in gene expression induced by Egr-1 in human fibroblasts at the genome-wide level." (PMID 21931594, 2011). "In contrast, in acute toxic injury (e.g., CCl4-induced fibrosis), EGR1 facilitates tissue repair by supporting normal wound-healing responses, and its absence worsens fibrosis." (PMID 40950963, 2025). "These enriched functions were mainly related to the function of Egr1, which is it mediates mesothelial fibrosis and prompts migration of GC cells." (PMID 37989866, 2024). "In summary, this study identified IRX2 as a critical regulator of cardiac fibrosis via the transcriptional activation of EGR1." (PMID 37587150, 2023). "Thus, our data indicated that Egr1 is key molecules involved in the peritoneal mesothelial fibrosis promoted by HOXA11 over-expressed GC cells." (PMID 37989866, 2024).
heart failure (10 papers, 2013 to 2025). Inability of the heart to pump blood at an adequate rate to meet tissue metabolic requirements. "Previous studies have demonstrated the involvement of miRNAs in the regulation of EGR1 in cardiovascular disorders such as heart failure and myocardial infarction." (PMID 38926457, 2024). "Second, we identified EGR1, EGR2, FOS and FOSB as potential diagnostic biomarkers and therapeutic targets for heart failure." (PMID 36859608, 2023). "Through PPI network and logistic regression, we identified EGR1, EGR2, FOS and FOSB as potential diagnostic biomarkers and therapeutic targets for heart failure." (PMID 36859608, 2023). "Egr-1 has been linked with multiple cardiovascular disorders including reperfusion injury, myocardial fibrosis, no reflow and heart failure." (PMID 39619154, 2024). "In addition, we identified EGR1, EGR2, FOS and FOSB as potential diagnostic biomarkers and therapeutic targets for heart failure." (PMID 36859608, 2023).
renal failure (10 papers, 2017 to 2024). "In cases of acute kidney injury, the rapid and transient induction of EGR1 serves a renoprotective role in facilitating kidney repair." (PMID 39301055, 2024). "Current therapeutic options for AKI are limited to renal dialysis or transplantation, and, thus, Egr-1 and its downstream have potential therapeutic benefits in alleviating renal tubular injury and preventing renal failure in patients." (PMID 37762598, 2023). "Egr-1 expression is also elevated in renal failure patients, and persistent expression of Egr-1 is shown to aggravate nephrotic progression in many chronic kidney diseases." (PMID 37762598, 2023). "Egr1 disruption protected mice from renal failure in a model of tubulointerstitial nephritis and resulted in lower activation of the TGF-β pathway." (PMID 31773180, 2019). "Egr1 aggravates renal failure via facilitating NF-κB-mediated renal innate immunity." (PMID 29681936, 2018). "As Egr-1 activity is elevated in renal tubular cells in patients with renal failure, this may be related to Egr-1, which mediates the TGF-β signaling pathway in the kidney, immune cell infiltration, and regulates the NF-κB activity and cytokine/chemokine expression in the kidney." (PMID 31357612, 2019). "Moreover, we verified the differential expression of Egr1, Jun, and Cxcl2 in the IRI mouse model and acute kidney injury human samples." (PMID 38753279, 2024).
Alzheimer disease (9 papers, 2013 to 2025). A progressive, neurodegenerative disease characterized by loss of function and death of nerve cells in several areas of the brain leading to loss of cognitive function such as memory and language. "egrh‐1 is the ortholog of human EGR1 (early growth response 1), a major transcription factor that has been implicated in multiple diseases including cancer, neuropsychiatric disorders, and Alzheimer's disease." (PMID 36404134, 2023). "In mice, loss of EGR1 has been linked to neuronal loss in a model of Alzheimer’s disease." (PMID 28754123, 2017). "Indeed, lower Egr1 mRNA and protein levels in our mouse model are in line with downregulated RNA levels of Egr1 in hippocampal tissue of Alzheimer's disease models." (PMID 29755323, 2018). "Moreover, EGR-1 is up regulated in brain of patients with Alzheimer disease (AD), and overexpression of EGR-1 controls both phosphorylation and dephosphorylation of tau, by activating CDK5 and inactivating PP1, leading to tau hyperphosphorylation and destabilized microtubules." (PMID 24066134, 2013). "Intriguingly, we found Egr1 and other IEGs responding specifically in TGEE mice, agreeing with reports of similar effects in a mouse model for Alzheimer's disease." (PMID 29755323, 2018).